ISG15 (ISG15 ubiquitin like modifier)
Diseases named in the same sentence as ISG15 in open-access papers (continued):
Sharing a sentence is not in itself a finding about the gene and the disease.
viral infection (continued). "Interestingly, ISG15-deficient patients do not have enhanced susceptibility to viruses suggesting ISG15 is not necessary to control ubiquitous viral infections in vivo." (PMID 38384473, 2024). "Altogether, our work highlights an essential role for ISG15/ISGylation in viral infection and cell-to-cell spread and points out the relevance of the comprehension of ISG15-mediated antiviral responses, which might lead to the development of effective therapies against relevant human pathogens." (PMID 37036376, 2023). "Thereby, mice lacking ISG15 were shown to be modestly more susceptible to some but not all viruses, while humans with ISG15 deficiency have overactive antiviral responses and no documented susceptibility to viral infections." (PMID 35333911, 2022). "However, the role of ISG15 in viral infection remains controversial." (PMID 36315588, 2022). "Therefore, the regulation of cell metabolism should be included in the array of indirect antiviral activities performed by ISG15, together with the modulation of protein activity and turnover, the modulation of immune responses, and the control of genome stability during viral infections." (PMID 36453897, 2022). "However, from 1 day after viral infection, the expression of the ISG15 and Mx genes in rVHSV-P-infected fish was up-regulated and, at 3 days after viral infection, their expression in rVHSV-P-infected fish increased to levels similar to those found in rVHSV-wild-infected fish." (PMID 33465148, 2021). "Moreover, CCL18 from ISG15-treated TAMs may establish a loop between viral infection, TAMs and tumor progression." (PMID 33424843, 2020). "Furthermore, the production of Ifnb, Isg15, and Ccl5 was increased in Arrb2−/− mouse embryonic fibroblasts (MEFs) transfected with K171R mutant compared with WT β-arrestin 2, whereas K171Q mutant abolished the positive regulation during virus infection." (PMID 33243993, 2020). "On the other hand, it is interesting to note that whilst in murine studies ISG15−/− mice are generally more sensitive to disseminated viral infections human patients presenting with primary immunodeficiencies associated with defects in ISG15 expression are not." (PMID 31921100, 2019). "Though mature form of ISG15 conjugation to target proteins was shown to be essential for ISG15-dependent antiviral effects, both free ISG15 (intracellular or extracellular) and ISGylation could be detected, indicating potential functions of free ISG15 involved in viral infection." (PMID 27867263, 2016). "As ISG15 is strongly induced by various types of external stimuli, such as virus infection, LPS, genotoxic stresses and retinoic acid, we then investigated whether ISG15 conjugation to parkin occurs in response to other selected signals, such as LPS, camptothecin (CPT) and etoposide (Eto)." (PMID 27534820, 2016). "In addition, ISG-15 protein, a ubiquitin-like modifier, greatly expressed after Type I interferon stimulation has been shown to mediate protection in a number of different viral infection models." (PMID 25610463, 2014). "However the relative levels were significantly lower in the ISG15−/− macrophages, suggesting that viral infection could be blocked in an early step in these cells." (PMID 24137104, 2013). "For example, viral infection and poly(I:C) treatment activate the expression of the ISG15 of Atlantic cod, Atlantic salmon, black rockfish, channel catfish, crucian carp, and Japanese flounder, while bacterial challenge activates ISG15 expression in Atlantic cod, goldfish, and red drum." (PMID 23028660, 2012). "The highest ratio in this set was two-fold and out of the top 10 specificities, 7 were in the Type I interferon signature (IFITM3, MX1, IFI6, IFI44L, ISG15, OAS1, IFIT3) and one encodes a protein that is activated by dsRNA as might be present in a viral infection (EIF2AK2)." (PMID 21366908, 2011).
viral infection (continued). "ISG15 is one of scores of ISGs which may be induced directly or indirectly by virus proteins or byproducts of virus infection; however, as expression of ISG15 mRNA and protein was similar between ΔNS1/2 and WT virus infection of MLE-15 cells, it is unlikely NS1/NS2 has a role in modifying ISG15." (PMID 18851747, 2008). "ISG15 is one of the most commonly induced genes by type I IFN signaling, and it plays a critical role in defending against viral infections." (PMID 40431442, 2025). "Recent research has focused on the role of ISG15 in SARS-CoV-2 and other viral infections, indicating that it has both anti- and pro-viral effects, acting as a post-translational modifier or a “cytokine-like” molecule during infection." (PMID 41000193, 2025). "Meanwhile, the transcriptional levels of interferon-stimulated genes (ISGs) such as ISG15, ISG20, OAS1, OAS2, MX1, and MX2 were significantly up-regulated, and these ISGs play a crucial role in resisting viral infection." (PMID 41153955, 2025). "Here we showed that the ability of ISG15 mutants to bind USP18 mirrored the gradient pattern of ISG mRNA regulation and corresponding effects on viral infection." (PMID 39931755, 2025). "Viral infections trigger the production of type I interferons (IFNs), such as IFN-alpha and IFN-beta, which stimulate ISG15 production and promote ISGylation." (PMID 40284971, 2025). "During viral infections, host cells increase IFN-α/β levels, thus enhancing ISG15 synthesis in both infected and neighboring cells." (PMID 40103488, 2025). "In turn, IFNs induce the production of hundreds of ISGs, including ISG15, IFIT1, and RIGI itself, in a process that aims to control virus infection." (PMID 39403383, 2024). "Many of the genes corresponding to this factor such as IFI27, ISG15, IFITM3 are parts of the type 1 interferon signaling pathway normally observed in viral infections." (PMID 39369208, 2024). "An interruption to the conjugation of ubiquitin and ISG15, affects IFN signaling, NFκB or signal transducer and activator of transcription 1 (STAT1), and other genes essential for the rapid response against viral infection." (PMID 39599842, 2024). "We thus investigated the expression of four ISGs acting on different steps of viral infection (i.e., OAS1, IFITM3, ISG15, MxA) in lysates of HAEs infected with A/H3N2, A/H1N1, D614G and Omicron viruses in single and coinfections." (PMID 39038029, 2024). "ISG15 is a UBL protein stimulated upon IFN treatment and largely studied for controlling viral infection." (PMID 38781019, 2024). "VirSig was defined as the signature of the host response to viral infection using the average expression of five representative genes, including IFI27, RSAD2, IFI44L, ISG15 and IFITM3." (PMID 38790931, 2024). "To further compare the presence of free and bound ISG15 after treatment with Bacillus subtilis, we detected the blank group, PRV group, Bacillus subtilis group and Bacillus subtilis + PRV group 12 h after virus infection." (PMID 37256060, 2023). "In nasal macrophages, an abundantly induced ISG, ISG15 (ENSG00000187608), is crucial for viral infection." (PMID 37007947, 2023). "For instance, one of the most highly inducible ISGs, ISG15 ubiquitin like modifier (IFN-stimulated gene of 15 kDa; ISG15), is expressed by cardiomyocytes in response to the type I IFN IFN-β, and it is induced in cardiomyocytes in response to viral infection." (PMID 37115698, 2023). "Viral infection, represented by SARS-COV-2 infection, and type I IFNs induced expression of ISG15 and the predominant E3 ISGylation ligases HECT domain- and RCC1-like domain–containing proteins (HERCs; HERC5 in humans and HERC6 in mice)." (PMID 37651190, 2023). "Previous studies of viral infections have revealed the existence of IFNAR-independent pathways mediating the expression of ISGs, such as IFIT1, IFIT2, IFIT3 and ISG15, all of which were expressed by FVB/N macrophages during priming with M. ulcerans antigens." (PMID 37428812, 2023).
viral infection (continued). "RT-qPCR substantiated this observation, demonstrating that overexpression of circMerTK reduced the levels of IFN-β, ISG15, and MX1 mRNA following viral infection compared to the empty vector control." (PMID 36847523, 2023). "Especially, many ISGs were modified with ubiquitin during viral infections such as MX1, MX2, OAS2, ISG15, and ISG20, which has rarely been reported before." (PMID 36071039, 2022). "We validated the relevance of MX1, MX2, ISG15, and OAS1 in the context of viral infections in cell cultures in vitro and in a pre-clinical model of Coronavirus infection." (PMID 36298734, 2022). "It has been reported that interferon can significantly trigger the production of many interferon-induced genes (IFIT1, IFITM3, MX-1, OASL, ISG15, PKR, GBP1, Viperin, BST2, IRF-1, and CXCL10), which play key roles in the resistance to viral infection." (PMID 36337195, 2022). "Interferon-stimulated gene 15 (ISG15), an IFN-α/β-inducible, ubiquitin-like molecule, has been reported to play an antiviral role in viral infection." (PMID 36146669, 2022). "E3 ligase HECT and RCC1-containing protein 5 (HERC5) regulate interferon-stimulated gene 15 (ISG15) signaling in response to SARS-CoV-2 and other viral infections." (PMID 36510222, 2022). "More recently, ISG15 was reported to have an immunomodulatory effect by acting as a negative regulator of IFN-I signaling, thus regulating the antiviral response during viral infection." (PMID 36315588, 2022). "In type I IFN receptor R1 knockout mice and cells, ISG15 expression is attenuated upon treatment with LPS or viral infections, suggesting that activation of type I IFN signaling by bacterial and viral infections induces ISG15 expression." (PMID 36319753, 2022). "Type I interferons (IFN-α/β) protect other cells from further viral infection by binding to IFN-α/ß receptors, leading to induction of antiviral proteins such as Mx, ISG15 and protein kinase R (PKR)." (PMID 35046944, 2021). "ISG15, IRF7, MX1, RSAD2, and IFIT3 have been found to play a vital role in modulating immune response against the viral infection." (PMID 34631844, 2021). "Thus, ISG15 may play a key role in inhibiting viral infection." (PMID 34901029, 2021). "The different consequences of PKR on Mx1, ISG15, and CCL5 expression kinetics suggest that, although all these genes are overall upregulated upon viral infections, they are also differently tuned by additional host factors such as PKR." (PMID 34372519, 2021). "Meanwhile, IFI6, IFITM2, ISG15, and LDHB were highly expressed in memory CD4+T cells, which were crucial for cell hypermetabolism and defense against virus infection." (PMID 35095832, 2021). "Recent biochemical studies have demonstrated how the E3 ligase HECT and RCC1-containing protein 5 (HERC5) regulates ISG15 signaling in response to hepatitis C (HCV), influenza-A (IAV), human immunodeficiency virus (HIV), SARS-CoV-2 and other viral infections." (PMID 34207696, 2021). "It is relevant to consider that MSC are usually resistant to viral infection due to their expression of interferon (IFN), and, subsequently, IFN-stimulated genes (ISGs) (such as IFI6, ISG15, SAT1, PMAIP1, p21/CDKN1A, and CCL2)." (PMID 33808241, 2021). "Interestingly, ISG15 deficiency in mice leads to increased and often deadly viral infections, but in humans seems to involve increased susceptibility to mycobacteria and dysregulated immune responses rather than viral infections." (PMID 32429099, 2020). "The components of this minimal gene signature related to IL-6 include DHX58, IFIH1, ISG15, and PNPT1, which it shares with the gene signature observed after yellow fever vaccination." (PMID 33244316, 2020). "However, ISG15-null patients appear not to be more susceptible to viral infections." (PMID 32039148, 2019).
viral infection (continued). "We extended our analysis to a range of ISGs that have previously been identified as being regulated directly by virus infection in an IFN-independent manner i.e., IFIT1, IFIT2, IFIT3, ISG15, CXCL10, Mx1 and Mx2." (PMID 30871003, 2019). "Confirming our initial findings, viral infection of PVG rats increased the expression of Th1 and type I IFN target genes (MX1, ISG15, IRF7, and CXCL10)." (PMID 30150981, 2018). "ISG15 belongs to the group of type I IFN–inducible genes and is highly induced after type I IFN–generating viral infections." (PMID 29891555, 2018). "To confirm these results we also studied by qPCR mRNA production of IFNβ and IFNβ-dependent genes such as Isg15, CXCL10 (an established marker of viral infection) or MX1." (PMID 29958295, 2018). "Both ISG15 and IFIT1 are found to be induced rapidly and robustly after IFN stimulation upon viral infection." (PMID 28869524, 2017). "UbcH8 acts as an ISG15-conjugating enzyme when cells are stimulated with IFN, lipopolysaccharide (LPS) or viral infection." (PMID 27534820, 2016). "HCMV-induced ISG15 expression was mitigated by IE1, a viral inhibitor of interferon signaling, however, ISGylation was still strongly upregulated during virus infection." (PMID 27564865, 2016). "After viral infection, KIOM-C-treated RAW264.7 cells induced the antiviral (PKR, OAS, Mx-1), IFN-β and IFN-stimulated genes (ISG-15 and ISG-56) both at 12 and 24 hpi." (PMID 25942440, 2015). "Driver genes of this sub-network (OAS2, ISG15, STAT1, and ADAR) are involved in immune response to viral infections, and expression of these genes is inducible by interferon." (PMID 25868721, 2015). "Several interferon-inducible genes involved in immune response to viral infection (including OAS2, ISG15, STAT1, and ADAR) were identified as “drivers” in this sub-network based on the ARACNE and key driver analysis." (PMID 25868721, 2015). "Among these, the expression of Mx1, Mx2, TRIM22, WARS, ISG15, ISG20, UBA7, DDX58, and OAS1-3 were up-regulated, representing an increased innate immune response against viral infections." (PMID 25883591, 2015). "Consequently, our results suggest that the interconnection between IFN response and the AKT pathway could be at the base of the increased susceptibility to viral infection in the absence of ISG15." (PMID 24137104, 2013). "Covalent linkage of the ubiquitin-like protein ISG15 interferes with viral infection and USP18 is the major protease which specifically removes ISG15 from target proteins." (PMID 22916876, 2012). "Virus infection, or expression of this OTU domain in transfected cells, led to a great reduction in the incorporation of ubiquitin or ISG15 protein into host cell proteins." (PMID 22163042, 2011). "Human ISG15 expression is strongly up-regulated during viral infections, such as human cytomegalovirus (HCMV) and herpes simplex virus (HSV), and ISG15 up-regulation was considered to be involved in different strategies relating to the antiviral response." (PMID 22078027, 2011). "ISG15, a ubiquitin-like protein, is one of the IFN-stimulated genes (ISGs) induced most rapidly and strongly by type I IFNs, as well as by viral infection and LPS." (PMID 22140447, 2011). "ISG15 and its conjugation modification play roles in processes including regulation of IFN signaling, innate immunity, anti-viral infections, pregnancy, and carcinogenesis." (PMID 20569475, 2010). "ISG15 is one of the most abundantly-induced transcripts upon type I IFN treatment, as well as following TLR ligation and viral infection." (PMID 21994614, 2010). "The observed elevation of ISGs, encompassing ISG15, IFI6, IFIT1, IFIT2, IFIT3, IFI44L, and IFITM3, highlights SARS-CoV-2’s ability to activate the host’s interferon response—a critical defence mechanism against viral infection." (PMID 39940816, 2025).
viral infection (continued). "We then evaluated the expression of four interferon-stimulated genes (ISGs) acting on different steps of viral infection (i.e., OAS1, IFITM3, ISG15, and MxA) in lysates of nasal HAEs infected with each single virus or coinfected with the two viruses simultaneously or sequentially 1 or 4 days apart." (PMID 40366152, 2025). "Another study highlighted how the absence of ISG15 impacts macrophage lipid metabolism in the context of viral infections." (PMID 38397063, 2024). "In the absence of viral infection, the conjugation of ISG15 to actively translated host proteins can affect several cellular processes including cytoskeletal dynamics, DNA damage responses, cytokine release, and immune modulation." (PMID 38665231, 2024). "Furthermore, viral infection induces expression of ISGylation enzymes, including UBE1L, UBCH8, ISG15, and HERC5, suggesting that ISGylation is involved in host defenses against viruses." (PMID 37651190, 2023). "In the absence of viral infection, but in the presence of pressure overload and compensatory cardiomyocyte enlargement, ISG15 conjugates to actively translated cellular proteins." (PMID 37115698, 2023). "This trend follows for the other ISG transcripts analyzed, with ISG15 having an approximately 7.1-fold increase, IFIT1 an 11.7-fold increase, and OASL a 13.2-fold increase in transcripts in the C7/10-derived virus infection compared to the BHK-derived virus infection." (PMID 37632027, 2023). "Products of ISG15 and ISG20 are functionally different proteins—a ubiquitin-like modifier and an exonuclease, respectively, although both ISG15 and ISG20 belong to interferon-stimulated genes and are involved in the innate immune response to viral infection." (PMID 37998351, 2023). "Up-regulated differentially expressed genes (DEGs) indicated a clear relationship with the innate immune response against viral infection, including genes coding PRRs (LPG2 or DHX58) and IFN-stimulated genes (ISG15, Mx, STAT1, HERC5, IFI44, IFIT-1, NUP133, TRIM21)." (PMID 35215144, 2022). "In this work, we highlight how the absence of ISG15 impacts macrophage lipid metabolism in the context of viral infections and how poxviruses modulate metabolism to ensure successful replication." (PMID 36453897, 2022). "In 2012, an AR complete ISG15 deficiency was found in three patients with MSMD who suffered from BCG disease, but not viral infections." (PMID 36569938, 2022). "Another possibility is that ISG15 accumulation may promote IFN-I signaling and/or the expressions of ISGs to combat viral infection." (PMID 36315588, 2022). "Based on these results, we hypothesize that the similarities between the proteomic profiles of uninfected Isg15−/− BMDMs and VACV-infected WT BMDMs might be due to reduced ISG15 levels in the context of viral infection or IFN stimulation." (PMID 36453897, 2022). "However, during viral infection, the expression of ISGs including DHX58, IFITM3, ISG15, and OASL was upregulated in the livers of WT mice, while Neurl3−/− livers expressed a higher level of proteins related to inflammatory response such as S100A9 and CD47." (PMID 35792897, 2022). "The ESCRT, complex, ALIX-CHMP4A, is recruited to NS3 through their interactions with the putative L domain motif of NS3, while CHMP4A is recruited to E. In addition, we demonstrate the antiviral mechanism of ISG15 and HERC5, which degrades ALIX and CHIMP4A, indirectly targets virus infection." (PMID 34851141, 2022). "We speculate that IFI27, BST2, MX1 and ISG15 may play an important role in the suppression of ZIKV and other viral infections rendered by NS4A." (PMID 35522620, 2022). "We also observed no ISG15 protein expression by immunofluorescence microscopy in the lungs of FGF9-OE mice following treatment with DOX but without viral infection." (PMID 35675358, 2022).